ALB (albumin)
Diseases named in the same sentence as ALB in open-access papers (continued):
Sharing a sentence is not in itself a finding about the gene and the disease.
diabetes (continued). "Other variables associated with total IS levels were diabetes mellitus, albumin, and creatinine." (PMID 36278836, 2022). "Reports indicate that inflammatory markers, such as low serum albumin, are a risk for diabetes." (PMID 35290727, 2022). "The final CKD risk factors consisted of age, duration of diabetes, insulin use, estimated glomerular filtration rate, albumin-to-creatinine ratio, high-density lipoprotein cholesterol, triglyceride, diabetes retinopathy, variation in HbA1c, variation in FPG, and hypertension drug use." (PMID 35314714, 2022). "Diabetes is an independent risk factor for PLIF, which may be associated with diabetes-induced vascular permeability changes and perioperative proteinuria, leading to increased albumin loss." (PMID 34717707, 2021). "Reduced albumin was reported to be associated with an unfavorable metabolic profile, characterized by increased adipose tissue inflammation, adiposity, and glucose and with an increased risk for type 2 diabetes mellitus." (PMID 34357115, 2021). "Diabetes, low calf circumference, and low albumin were independent risk factors for malnutrition." (PMID 33919840, 2021). "In univariate analysis using age, gender, BMI, albumin, co-morbidities (ischemic heart disease, diabetes mellitus and CKD), gastrectomy type, pStage, blood loss and operative time as covariates, variables associated with anastomotic leak were male, severe CKD, total gastrectomy and blood loss." (PMID 33930090, 2021). "Furthermore, in women with T2DM, WHtR has been shown to be independently and better associated with elevated urinary albumin excretion rate, a common cardiovascular risk factor in diabetes, than WC, WHR, and BMI." (PMID 34692623, 2021). "Diabetes was associated with increased urine albumin-to-creatinine ratio in both animal models." (PMID 34073747, 2021). "Moreover, age, sex, history of diabetes mellitus, and hemoglobin and albumin levels were consistently correlated with all-cause mortality in all the three models (p < 0.05)." (PMID 34785712, 2021). "Body mass index, diabetes mellitus, hypertension, and albumin were risk factors for AKI." (PMID 33916162, 2021). "Univariate Cox regression analysis showed that age, BMI, NYHA class, diabetes mellitus, atrial fibrillation, smoking, eGFR, lg NT-proBNP, hemoglobin, albumin, LDL-C, and LEV were associated with MACEs (unadjusted hazard ratio 1.305, 95% CI 1.152–1.485, P < 0.0001)." (PMID 34901210, 2021). "Moreover, less than half of the patients were tested for urinary albumin, an early marker of kidney disease caused by diabetes." (PMID 34276558, 2021). "However, p-values < 0.05 were significant for body-mass index (BMI), diabetes mellitus as a cause of end-stage renal disease, and serum albumin levels." (PMID 34301316, 2021). "According to our baseline dataset, the traditional risk factors age, diabetes, albumin level and cardiovascular disease were significantly different between the surviving patients and patients who experienced premature mortality, consistent with the findings of previous studies." (PMID 33988129, 2021). "Our study showed that proteinuria was an independent risk factor for AKI development among patients with diabetes and COVID-19; this finding supports previous studies underlining the strict relationship between albumin excretion rate and cardiorenal outcomes in diabetic nephropathy." (PMID 33506050, 2021). "Sarcopenia was diagnosed in 28.1% of the patients, and a univariate analysis showed that age, BMI, diabetes, hypertension, blood pressure, eGFR, hemoglobin, serum levels of total cholesterol, protein, albumin, total CO2, and total calcium were associated with sarcopenia." (PMID 34531464, 2021). "Increased mortality was associated with higher age, CKD stages 3–5, albumin/creatinine ratio, diabetes mellitus, active smoking, prior MI, valvular heart disease, peripheral artery disease, and slightly as well as severely reduced left-ventricular ejection fraction." (PMID 34036426, 2021).
diabetes (continued). "Now, it is well known that albumin properties incur some changes under: (i) ischemic attacks associated with oxidative stress; (ii) the production of ROS; (iii) the development of acidosis and diabetes mellitus (DM) and its complications." (PMID 34943049, 2021). "However, in some patients with normoalbuminuria, a reduced glomerular filtration rate (GFR) was observed, indicating that significant glomerular damage has already occurred before the albumin detection." (PMID 32194418, 2020). "The oxidation of serum albumin may cause neutrophil activation and further oxidation of albumin in diabetes, which are important in the severity and progression of DKD." (PMID 33092580, 2020). "In addition, time to dialysis was associated positively with age, albumin, and eGFR at enrollment but negatively with diabetes." (PMID 32200348, 2020). "In particular, increase of serum globulins can be associated with diabetes mellitus, rheumatoid disease, chronic liver disease, nephrotic syndrome, and cancer; whereas decrease of albumin can be associated with chronic liver disease, chronic infections, and nephrotic syndrome." (PMID 32686760, 2020). "This study bridges structural findings with our analysis of publicly available clinical data from Wuhan and suggests that an adjustment of dexamethasone regimen should be considered for patients affected by two major COVID-19 risk-factors: low albumin levels and diabetes." (PMID 32743572, 2020). "Finally, the multivariate regression analysis showed that diabetes, low calf circumference, and low albumin levels were independent risk factors for malnutrition in these subjects." (PMID 32785121, 2020). "In addition, our findings suggest causal feedback loops between urinary albumin and hypertension, and urinary albumin and type 2 diabetes mellitus." (PMID 32008434, 2020). "The interactions between time and 9 conditions, namely diabetes, cerebrovascular accident, heart arrhythmia, coronary atherosclerotic heart disease, hypertension, cardiovascular disease, and ischemic heart disease were significantly associated with albumin." (PMID 32295526, 2020). "Increasing values of age, D-dimer, C-reactive protein, sequential organ failure assessment (SOFA) score and body temperature while decreasing albumin, and a history of diabetes were the risk factors with the highest consistency as predictors for covid-19 severity." (PMID 32491116, 2020). "The group of patients suffering a CVE were older, predominantly males, with a higher body mass index, systolic blood pressure and urine albumin to creatinine ratio, and showed an increased proportion of other classical cardiovascular risk factors (smoking, diabetes, hypertension, and dyslipemia)." (PMID 31036794, 2019). "The results of pooled analysis in the present study, which was solely conducted on patients with diabetes, showed that the pooled OR of the association between sarcopenia and urinary albumin level was 2.11, which is consistent with the findings of a previous study." (PMID 31828155, 2019). "However, there were significant differences in gender, age, BMI, previous laparotomy, jaundice, cholangitis, weight loss, tumor size, levels of ALB, preoperative bile duct drainage, diabetes, and pancreatic duct diameter between the two groups (all P < 0.05)." (PMID 30611270, 2019). "The history of urinary diagnostic testing spans from diagnosis of diabetes mellitus by tasting urine for unusual sweetness to the use of urinary minerals (e.g., sodium) or proteins (e.g., albumin) to characterize disease to the current exploration of urinary extracellular mRNA." (PMID 31285998, 2019). "Proteinuria has been associated with increased transcapillary escape rates of albumin in patients with diabetes and essential hypertension, and it has also been suggested that this could reflect a generalized vasculopathy secondary to endothelial damage." (PMID 29423043, 2018).
diabetes (continued). "DKD is commonly diagnosed by reduced estimated glomerular filtration rate (eGFR < 60 mL/min/1.73 m2) and/or increased urinary albumin excretion (> 30 mg/g creatinine), a marker of kidney damage, that persist ≥3 months in the presence of longstanding diabetes and exclusion of other causes of CKD." (PMID 29457196, 2018). "Moreover, these values were associated with pH, HD duration, serum albumin concentration, and the presence of diabetes mellitus (DM)." (PMID 29940017, 2018). "For prognosis, HOP predicted composite events in patients at stages C and D, independent of log (BNP), age, sex, left ventricular ejection fraction, New York Heart Association functional class, HF stage, diabetes mellitus, chronic kidney disease, hypertension, hemoglobin, and albumin." (PMID 30405858, 2018). "A multivariable logistic regression model showed that in lower BMI patients the presence of peripheral vascular disease, heart failure, diabetes mellitus, and malignancy, and higher urea and lower albumin blood levels were risk factors associated with dying in the first year." (PMID 30150623, 2018). "Finally, in glomeruli isolated from rats with early diabetes there was a significant increase in albumin permeability and loss of endothelial glycocalyx, both of which were ameliorated by angiopoietin-1." (PMID 29433915, 2018). "Previously reported associations between low serum albumin and higher risk of diabetes and cardiovascular disease are partially explained by this hypothesis." (PMID 28430803, 2017). "Urinary albumin is an important biomarker used to identify high risk patients with diabetes, but there is a need for new biomarkers that alone or in combination with urinary albumin could give an even better prediction of clinical patient outcomes." (PMID 28666207, 2017). "Urinary albumin is an important biomarker used in the identification of high risk diabetes patients, but there is a need for new biomarkers that alone or in combination with urinary albumin could give an even better prediction of clinical patient outcomes." (PMID 28666207, 2017). "It is possible that for patients with diabetes, hypertension, and obesity, cardiovascular risk assessment including albumin measurement for identification of CKD and more strict management of underlying disorders may improve prognosis." (PMID 27169575, 2016). "Several diseases such as HIV, acute infection, burns, diabetes, a condition that causes albumin decrease, taste disorder, nephritic syndrome, inflammatory diseases, malabsorption, Crohn's disease, myocardial infarction, etc., the concentration of zinc is reduced." (PMID 25965704, 2015). "Lower heart rate variability was significantly associated with older age, female gender, diabetes, higher heart rate, C-reactive protein and phosphorus, lower serum albumin, higher high-density lipoprotein, and stage 5 chronic kidney disease in patients with nondialysis chronic kidney disease." (PMID 24982887, 2014). "For participants with 25(OH)D < 50 vs ≥50 nmol/L, cardio-metabolic risk profile differed for: diabetes (54%, 36% p < 0.001), past history of cardiovascular disease (16%, 9%, p = 0.014), waist-hip ratio (0.98, 0.92, p < 0.001), urine albumin-creatinine ratio (2.7, 1.5 mg/mmol, p < 0.001)." (PMID 25197323, 2014). "Diabetes appeared to have caused lower Mn based on data showing low stores of albumin and other binding proteins in diabetic patients, suggesting that Mn and diabetes may affect each other." (PMID 24606630, 2014). "Regression analysis showed that mean albumin associated with nPCR, fever, hospital stay, bacteremia, dialysis vintage, age, sex, and diabetes mellitus; and that an albumin level of <3.8 g/dl associated with age, female sex, diabetes, lower nPCR, and higher ferritin." (PMID 24499139, 2013). "Diabetes caused an increase in urinary albumin to creatinine (UACR) ratio (P<0.01) in dKO mice." (PMID 23874911, 2013).
diabetes (continued). "In the EPIC-NL case-cohort study, stratified analysis by sex showed that the direction of the association between albumin and diabetes risk was changed in men after adjustment for age, BMI with family history of diabetes (also for the KORA basic model plus glucose) (data not shown)." (PMID 23284703, 2012). "The associations between GFR, CVD, diabetes, decreased Hb- and p-albumin levels and impaired HRQoL might be expected and are congruent with findings in other studies." (PMID 22710013, 2012). "We examined predictive value of combination of the Liver function tests (gamma-glutamyltransferase, alanine aminotransferase, aspartate aminotransferase and albumin) above validated models for 7.5-year risk of diabetes (the Cooperative Health Research in the Region of Augsburg, the KORA study)." (PMID 23284703, 2012). "However, in a multivariate hazard model using significant factors in single variate analyses, older ages, higher BUN, lower albumin, male gender and diabetes were significant risk factors of death after PEG formation." (PMID 27785173, 2012). "It is worth emphasizing that in metabolic diseases such as diabetes, albumin may undergo glycation and nitration, which cause substantial structural and functional modifications in its protein configuration." (PMID 22844592, 2012). "The reason for this could be that plama OPG levels were both associated to diabetes related parameters (i.e. HbA1c and U-albumin creatinine ratio) as well as to atherosclerotic related parameters (i.e. carotid arterial disease)." (PMID 21838881, 2011). "An elevated level of glycated albumin (GA) is a characteristic of diabetes; thus, it may be involved in monocyte/macrophage-associated diabetic complications." (PMID 21266043, 2011). "We hypothesized that compared with week 2 (food secure: period of food budget adequacy), week 4 (food insecure: period of food budget inadequacy) will be characterized by higher near-term diabetes risk biomarkers, that is, fasting glucose, fructosamine, and glycosylated albumin." (PMID 40153605, 2025). "Univariate logistic regression analysis showed that diabetes, infection, osteoporosis, psychiatric symptoms, blood glucose, blood sodium, erythrocyte count, hemoglobin count, white blood cell count, neutrophil count, eosinophil count, lymphocyte count, albumin, NLR and ELR were risk factors for AC." (PMID 39741879, 2024). "In addition to the well-known risk factors of lower serum albumin, older age, higher serum phosphorus levels, diabetes mellitus, and significant heart failure, a risk factor influencing mortality that differs from the conclusions of published articles was higher baseline eGFR." (PMID 38622550, 2024). "Hypertension, diabetes mellitus, and alcohol consumption had ORs greater than 1 and could be considered as independent risk factors for ischemic stroke, whereas albumin and HDL cholesterol had ORs less than 1 and could be considered as protective factors for ischemic stroke." (PMID 38682035, 2024). "In conclusion, in our high-risk cohort of African American and European American offspring of parents with type 2 diabetes, albumin excretion within the normal range at enrollment showed associations with cardiometabolic risk markers and the risk of progression from normoglycemia to pre-diabetes." (PMID 38233076, 2024). "Moreover, Hafez proved in their study that the level of urine NGAL in children with diabetes could be associated with an albumin-to-creatinine ratio, the duration of diabetes, glycated hemoglobin concentrations, and dyslipidemia." (PMID 37445650, 2023). "In contrast, GNRI calculated by albumin, actual body weight and ideal body weight is more objective and easily determined and it was associated with risk of deaths in many human diseases such as diabetes mellitus, cardiovascular disease, end stage renal disease and cancers." (PMID 36941480, 2023).
diabetes (continued). "Therefore, when albuminuria testing became a standard component of care for individuals with type 2 diabetes, the American Diabetes Association recommended albumin-creatinine ratios derived from spot urine collections as the new gold standard for albuminuria screening in diabetes." (PMID 38192517, 2023). "As for diabetes-associated complications, one published study and a pre-print study cross-sectionally evaluated serum sCD93 levels and markers of kidney function (i.e., serum creatinine, eGFR, proteinuria, and urinary albumin to creatinine ratio) in subjects with type 2 diabetes." (PMID 37371490, 2023). "The few published studies on the urinary albumin to creatinine ratio and all-cause mortality are aimed at smaller populations, relying on retrospectively collected data, or the population is a special population with underlying diseases such as diabetes and hypertension." (PMID 34983421, 2022). "Albumin has 16 histidine imidazole residues, which are major targets for a reaction with the lipid peroxidation product 4-hydroxynon-2-enal, the major product of membrane peroxidation that is linked to several diseases, such as Alzheimer’s and Parkinson’s, atherosclerosis, diabetes and cancer." (PMID 36142472, 2022). "Whether the associations of a history of cardiovascular disease, poor diabetes control, and indeed low serum albumin with fracture reflect concurrent vascular compromise in bone, or serve as indicators of an overall burden of disease and frailty in these individuals, remains unclear." (PMID 35677742, 2022). "In addition to valvular calcification, several factors, including age, duration of dialysis, phosphate and/or Ca×P product, oral calcium intake, use of vitamin D, diabetes, C-reactive protein, and low albumin, are generally associated with ectopic calcification." (PMID 34640403, 2021). "This retrospective study investigated the association between serum albumin level and HbA1c value and assessed the degree of influence that albumin has when levels exceed the HbA1c thresholds that are commonly employed for diagnosis and management of diabetes and pre-diabetes." (PMID 34055818, 2021). "Furthermore, low serum albumin concentrations have been shown to be associated with the severity of chronic inflammatory diseases, inflammatory bowel disease and diabetes mellitus, cirrhosis, as well as with the severity of surgical trauma, acute diseases and sepsis." (PMID 33511503, 2021). "For example, healthy subjects belonging to Cluster 1 who later develop diabetes may have a prominent oxidative stress component as alluded to by the inverse association with serum albumin and bilirubin, both of which are well-established circulatory antioxidants." (PMID 32134946, 2020). "However, we included almost all the major known risk factors for complications, including BMI, sarcopenia, diabetes mellitus, low albumin, total gastrectomy, and D2 lymphadenectomy; thus, we believe that this minimized the effect of the unmeasurable confounders." (PMID 31929799, 2019). "Similarly, increased serum globulins have been associated with cancer, rheumatoid diseases, chronic liver disease, nephrotic syndrome, and diabetes mellitus; decreased albumin has been associated with chronic infections, chronic liver disease, and nephrotic syndrome." (PMID 27931194, 2016). "In addition, after adjusting for age, albumin, 24-h urine volume, diabetes, and peritonitis, the risk of technical failure was 1.43 times higher in the elderly PD group, as compared to the younger PD group; however, the difference was not statistically significant (P = 0.220)." (PMID 26121574, 2015). "In a large, well-characterized cohort of obese dysglycemic subjects at risk for diabetes we found evidence for a statistically significant but weak inverse association between circulating adiponectin concentrations and urinary albumin excretion, measured as the albumin to creatinine ratio (ACR)." (PMID 26312480, 2015).